NRP1 (neuropilin 1)
Description:
Cell-surface receptor involved in the development of the cardiovascular system, in angiogenesis, in the formation of certain neuronal circuits and in organogenesis outside the nervous system. Mediates the chemorepulsant activity of semaphorins. Recognizes a C-end rule (CendR) motif R/KXXR/K on its ligands which causes cellular internalization and vascular leakage. It binds to semaphorin 3A, the PLGF-2 isoform of PGF, the VEGF165 isoform of VEGFA and VEGFB. Coexpression with KDR results in increased VEGF165 binding to KDR as well as increased chemotaxis. Regulates VEGF-induced angiogenesis. Binding to VEGFA initiates a signaling pathway needed for motor neuron axon guidance and cell body migration, including for the caudal migration of facial motor neurons from rhombomere 4 to rhombomere 6 during embryonic development (By similarity). Regulates mitochondrial iron transport via interaction with ABCB8/MITOSUR. (Microbial infection) Acts as a host factor for human coronavirus SARS-CoV-2 infection. Recognizes and binds to CendR motif RRAR on SARS-CoV-2 spike protein S1 which enhances SARS-CoV-2 infection. [Isoform 2]: Binds VEGF-165 and may inhibit its binding to cells. May induce apoptosis by sequestering VEGF-165. May bind as well various members of the semaphorin family. Its expression has an averse effect on blood vessel number and integrity.
Synonyms: CD304; NRP; VEGF165R; BDCA4; NP1
Tractability: Small molecule: a structure with a bound ligand is known; a high-quality ligand is known; it has a binding pocket of medium quality. Antibody: a drug acting on it is in phase 2 or 3 trials; UniProt places it where antibodies can reach, with high confidence; its Gene Ontology location is reachable by antibodies, with high confidence; UniProt predicts a signal peptide or a membrane-spanning region. PROTAC: ubiquitination databases record sites on it; its protein half-life has been measured; a small molecule that binds it is known.
Target class: Secreted protein
Gene: Protein-coding gene on chromosome 10 (33,177,492 to 33,336,262, reverse strand). Ensembl gene ENSG00000099250.
Subcellular location: Secreted (Isoform 2); Mitochondrion membrane; Cell membrane; Cytoplasm; Secreted
Subcellular location (Human Protein Atlas): Mitochondria; Predicted to be secreted
Pathways (Reactome):
Developmental Biology: CHL1 interactions; CRMPs in Sema3A signaling; SEMA3A-Plexin repulsion signaling by inhibiting Integrin adhesion; Sema3A PAK dependent Axon repulsion; Signal transduction by L1; Signaling by ROBO receptors
Disease: Attachment and Entry
Signal Transduction: Neuropilin interactions with VEGF and VEGFR
Gene Ontology:
Molecular function: growth factor binding; GTPase activator activity; protein binding; vascular endothelial growth factor binding; coreceptor activity; cytokine binding; semaphorin receptor activity; vascular endothelial growth factor receptor activity; protein kinase binding
Biological process: angiogenesis; cellular response to hepatocyte growth factor stimulus; endothelial cell chemotaxis; hepatocyte growth factor receptor signaling pathway; integrin-mediated signaling pathway; neuropilin signaling pathway; platelet-derived growth factor receptor signaling pathway; positive regulation of endothelial cell migration; positive regulation of filopodium assembly; positive regulation of focal adhesion assembly; positive regulation of stress fiber assembly; positive regulation of substrate adhesion-dependent cell spreading; regulation of Cdc42 protein signal transduction; substrate-dependent cell migration, cell extension; symbiont entry into host cell; vascular endothelial growth factor receptor signaling pathway; VEGF-activated neuropilin signaling pathway; angiogenesis involved in coronary vascular morphogenesis; animal organ morphogenesis; artery morphogenesis; axon extension involved in axon guidance; axon guidance; axonogenesis involved in innervation; basal dendrite arborization; basal dendrite development; and 53 more
Cellular component: cytoplasm; cytosol; extracellular region; focal adhesion; plasma membrane; axon; cytoplasmic vesicle; early endosome; neuron projection; receptor complex; semaphorin receptor complex; sorting endosome; glutamatergic synapse; membrane; mitochondrial membrane; neurofilament; postsynaptic membrane
Genetic constraint (gnomAD): Loss-of-function variants: 31 observed, 102.47 expected, observed/expected ratio (o/e) 0.3, 90% interval 0.23 to 0.41. The upper end of that interval is the gene's LOEUF score, 0.41, which puts it in group 1 of 6, group 1 being the genes least tolerant of losing a copy. Missense variants: 994 observed, 1,170.4 expected, observed/expected ratio (o/e) 0.85, 90% interval 0.81 to 0.89. Synonymous variants: 423 observed, 418.04 expected, observed/expected ratio (o/e) 1.01, 90% interval 0.93 to 1.1.
Gene-disease validity (ClinGen):
ClinGen rates the evidence that NRP1 causes each of these diseases.
congenital heart disease (autosomal recessive): Limited. A heart disease that is present at birth.
Homologues: Orthologues: chimpanzee NRP1 (99% identical), macaque NRP1 (99% identical), pig NRP1 (95% identical), mouse Nrp1 (93% identical), rat Nrp1 (93% identical), guinea pig NRP1 (91% identical), rabbit NRP1 (91% identical), tropical clawed frog nrp1 (72% identical), zebrafish nrp1a (65% identical). Paralogues in human: NRP2 (45% identical), CUBN (15% identical), CNTNAP5 (14% identical), CNTNAP4 (14% identical), F5 (13% identical), CNTNAP2 (13% identical), CNTNAP3B (13% identical), CNTNAP3 (13% identical), F8 (13% identical), HEPH (12% identical), NRXN2 (12% identical), CNTNAP1 (11% identical), and 23 more.
Diseases named in the same sentence as NRP1 in open-access papers:
NRP1 is named in the same sentence as 399 diseases in open-access papers, as found by Europe PMC text mining. Sharing a sentence is not in itself a finding about the gene and the disease. The quoted sentences say what the papers report.
breast carcinoma (174 papers, 2003 to 2026). "Given that overexpression of Poly (ADP-ribose) polymerase-1 (PARP1) and Neuropilin-1 (NRP1) is implicated in the pathogenesis of human breast cancer, the design of dual PARP1/NRP1 inhibitors has wide therapeutic prospect." (PMID 39679370, 2024). "Loss of NRP1 enhances cigarette-smoke-induced emphysema, facilitates NE uptake in breast cancer cells and resulting cytotoxicity, and serves as a co-receptor for ACE-2 during COVID-19 infection." (PMID 39684750, 2024). "Second, our data did not exclude the effect of VEGFR2 in this process, and we are interested in further investigating the precise mechanisms underlying VEGFR/NRP-1-related signaling in breast cancer cells." (PMID 38169627, 2024). "A recent study showed that NRP-1 knockdown was associated with reduced proliferation in triple-negative claudin-low breast cancer cells and prolonged survival in a claudin-low orthotopic mouse xenograft model using MDA-MB-231 cells." (PMID 37175499, 2023). "We report high NRP1 expression to be associated specifically with the claudin-low molecular subtype of breast cancer." (PMID 35078508, 2022). "These interactions have implicated NRP1 in cancer progression across multiple tumor types, where high NRP1 expression is associated with poor outcome in lung, glioblastoma, prostate and breast cancers." (PMID 35078508, 2022). "These include CHEK2 mutations in breast cancers and also in a variety of other cancers including thyroid cancer, EWSR1 in Ewing sarcoma, RET in hereditary medullary thyroid carcinoma, NRP1 in breast cancer and germline POT1 variants in malignant melanoma." (PMID 31614935, 2019). "Recently, we reported the expression of NRP-1 and other associated molecules in the plasma, immune cells, and tumor tissue of a breast cancer patients' cohort and confirmed the role of NRP-1, PlGF, and SNAI1 in breast cancer progression." (PMID 31106153, 2019). "It was reported that treatment of addicted melanoma cells with BRAF inhibitors and breast cancer cells with anti-HER2 drugs resulted in increased NRP1 expression, which was shown to have a causal role in resistance to these therapies." (PMID 30678134, 2019). "BT-474 NRP-1 variant cells were generated by stable overexpression of NRP-1 in the BT-474 breast cancer cell line." (PMID 29728077, 2018). "This is of importance to identify novel pathways associated with NRP-1 function with the purpose of dual targeting in breast cancer patients to increase treatment efficiency." (PMID 29728077, 2018). "This work supports the importance of NRP-1-associated molecules in circulation to characterize poor prognosis breast cancer and emphasizes on their role as favorable drug targets." (PMID 28607365, 2017). "Nrp1 has also been implicated in the migration and survival of breast cancer cells, however its potential role in MaSCs and in normal mammary development remains elusive." (PMID 28887477, 2017). "Our work illustrates that the upregulated levels of circulating NRP-1 and PlGF associate with nodal and distant metastasis in breast cancer." (PMID 28607365, 2017). "Our findings reinforced the close association between MMTV-Wnt1 mammary tumor and MaSCs2, 22, and suggested Nrp1 as a target to inhibit this type of breast cancer." (PMID 28887477, 2017). "In breast cancer, several studies have implicated NRP1 in various aspects of cell growth, survival, migration, and metastasis." (PMID 26967387, 2016). "Autocrine VEGF-VEGFR2-NRP1 signaling has also been reported to promote cancer stem cell maintenance in glioblastoma while NRP1 expression in breast cancer stem cells has been shown to be linked with the activation of NF-kB signaling." (PMID 26097868, 2015). "NRP-1 up-regulation appears to be associated with the tumor invasive behavior and metastatic potential, for instance in melanoma and breast cancer." (PMID 26090340, 2015).
breast carcinoma (continued). "Neuropilin-1 has also been implicated in chemotaxis of breast cancer cell lines through autocrine pathways involving both VEGF and SEMA3a by complexing with plexin-A1." (PMID 15956974, 2005). "Growing evidence has demonstrated that NRP-1 was frequently overexpressed and associated with poor prognosis in gastric cancer, melanoma, bladder cancer, cervical cancer, hepatocellular carcinoma, as well as breast cancer." (PMID 34374639, 2022). "Previous studies had proved that VEGF-A/NRP1 signaling might be associated with breast cancer metastasis." (PMID 36059555, 2022). "Moreover, despite evidence suggesting that NRP1 is implicated in breast carcinoma invasion, NRP1 expression on prostate cells was strongly and negatively correlated with the ability of these cell lines to invade and migrate." (PMID 33121034, 2020). "The sum of our results delineated that linc-OIP5 in breast cancer cells may act on the upstream of YAP1/Notch/NRP1 signaling circuit associated with tube formation abilities of HUVECs through an indirect cell–cell contact." (PMID 32046779, 2020). "It is well-established that NRP-1 is associated with the worst breast cancer outcomes." (PMID 31106153, 2019). "A truncated and thus noncyclic tumor-homing peptide tPlP-1 shows a promising possibility for targeting therapeutic and diagnostic agents to breast cancer cells, as it binds to both NRP1 and NRP2 and improves extravasation of co-injected nanoparticles into the tumor tissue." (PMID 30717262, 2019). "In addition, we detected high NRP-1 expression in breast cancer MDA-MB-231 parental and metastatic variant cells." (PMID 29728077, 2018). "Neuropilin-1 (NRP-1), a non-tyrosine kinase glycoprotein receptor, is associated with poor prognosis breast cancer, however transcriptomic changes triggered by NRP-1 overexpression and its association with chemoresistance in breast cancer have not yet been explored." (PMID 29728077, 2018). "Additionally, research has provided evidence that the signaling pathway involving vascular endothelial growth factor A (A) and neuropilin 1 (NRP1) plays a crucial role in promoting metastasis and invasion of breast cancer cells, which is often associated with a poor prognosis." (PMID 40003882, 2025). "Furthermore, recent evidence showed a close association of NRP-1 and breast cancer chemoresistance." (PMID 34374639, 2022). "Furthermore, we examined whether the levels of FOXO3a, VEGF-A, and NRP1 were associated with the survival of patients with breast cancer." (PMID 33262463, 2021). "Upregulated of E-cadherin and Occludin, but decreased levels of N-cadherin, Vimentin, and Snail expression were detected in the breast cancer cell lines upon VEGF or NRP1 silencing in the breast cancer cells." (PMID 40277760, 2025). "The expression levels of neuropilin-1 (NRP1) and glucose transporter 1 (GLUT1) in most tumors, including breast cancer, are closely linked to tumor proliferation and metastasis." (PMID 40048021, 2025). "Tumor cell lines such as prostate and breast carcinoma cell lines express abundant NRP1, nearly 1–2 × 105 receptors per cell." (PMID 40277760, 2025). "Another study by Nadejda and colleagues reported the overexpression of VEGF isoform (i.e., VEGF189) in MDA-MB-231 breast cancer cells induces apoptosis through NRP1." (PMID 40277760, 2025). "miR-376a-3p acts as a tumor suppressor in breast cancer by directly targeting neuropilin-1 (NRP-1), leading to the inhibition of Wnt/β-catenin signaling." (PMID 41009685, 2025). "The binding peptide TLTYTWS reduces angiogenesis in lung cancer models, and TM peptide inhibits tumor growth, angiogenesis, and migration in breast cancer by targeting neuropilin-1 (NRP1) receptors." (PMID 40612874, 2025). "We present this comprehensive transcriptomic dataset which provides a valuable resource for understanding both the transcriptomic landscape of claudin-low breast cancer and NRP1-regulated signalling pathways." (PMID 41326436, 2025).
breast carcinoma (continued). "Conversely, in glioblastoma and breast cancer studies, NRP1 is targeted by miR-124-3p and miR-376a, which suppress its expression." (PMID 40806445, 2025). "Further investigations are needed to study the specific effect of targeting NRP1 on the growth of breast cancer." (PMID 40277760, 2025). "The more aggressive breast cancers, such as triple-negative and Her-2 positive tumors, often have high levels of NRP-1." (PMID 39683699, 2024). "To determine the importance of ACE2 and NRP1 in mediating SARS-CoV-2 entry into the three breast cancer cell lines, we silenced ACE2 and NRP1 using specific short interfering RNAs (siRNAs)." (PMID 38849411, 2024). "The failure of exogenous hVEGF165 to stimulate the invasiveness and sphere formation of NRP-1-silencing breast cancer cells further supported the importance of NRP-1 in VEGFA-mediated signaling and function." (PMID 38169627, 2024). "NRP-1 was found to be elevated in multiple malignant tumors, such as breast cancer, lung cancer and gastric cancer 13-15, and participated in the promotion of tumor proliferation, epithelial-mesenchymal transition (EMT), invasion and migration 16-18." (PMID 38169627, 2024). "Another study showed that the knockdown of Linc-OIP5 suppressed the angiogenesis of the HUVECs through YAP1/Notch/NRP1 signalling in breast cancer." (PMID 39219375, 2024). "Meanwhile, Arpel and colleagues analyzed NRP1 inhibition in breast cancer models using a peptide that restricted NRP1 signaling, leading to a reduction in tumor growth and metastasis." (PMID 39685591, 2024). "Immunohistochemical analysis of breast cancer tissues showed that EDNRA was positively correlated with NRP1 expression." (PMID 39601333, 2024). "Poorer outcomes related to high NRP-1 levels have been reported for several tumor types and also in early breast cancer." (PMID 38468231, 2024). "Herein, we discovered novel small molecule inhibitors that simultaneously target PARP1 and NRP1 using structure-based virtual screening for the treatment of breast cancer." (PMID 39679370, 2024). "This glycoprotein together with a coreceptor called NRP1 (Neuropilin-1) forms a complex with VEGF receptors and causes angiogenesis in breast cancer." (PMID 38410788, 2024). "We revealed SEMA3F as a promoter of invasion during the DCIS-to-invasive ductal carcinoma transition in breast cancer (BC) through the action of NRP1 and NRP2." (PMID 39138514, 2024). "It has been shown that NRP1 is expressed in breast cancer spheroid cells and that the VEGF-A/NRP1 axis activates the Wnt/β-catenin pathway in breast cancer cells." (PMID 39679370, 2024). "Of note, NRP-1 has been studied as a prognostic factor mainly in early breast cancer by using immunochemistry." (PMID 38468231, 2024). "We previously reported that the ectopic over-expression of NRP-1 in the HER-2+ breast cancer cell line BT-474 was correlated with an upregulation of the TN-C/Integrinβ3/ITGB3) axis." (PMID 37175499, 2023). "Previously, we showed that elevation in circulating NRP-1 protein levels in the plasma of breast cancer patients is correlated with nodal and distant metastasis." (PMID 37175499, 2023). "For example, NRP1 is overexpressed in claudin-low breast cancer and promotes tumor progression via the RAS/MAPK pathway." (PMID 36841806, 2023). "NRP1 protein concentrations are significantly higher in breast cancer patients with lymph node involvement compared to those without lymph node involvement." (PMID 37894289, 2023). "NRP-1/VEGFR signaling was shown to enhance breast cancer EMT through the activation of NF-κB and β-catenin in MDA-MB-231 cells." (PMID 37175499, 2023). "It is shown that SEMA3A interacted with NRP1 to mediate MelCAM expression, leading to the suppression of breast cancer cell growth and angiogenesis." (PMID 37701532, 2023).